RN7SKP68 (RN7SK pseudogene 68)
Gene: Miscellaneous RNA gene on chromosome 5 (102,302,504 to 102,302,810, forward strand). Ensembl gene ENSG00000222987.
Homologues: Orthologues: chimpanzee 7SK (99% identical), guinea pig 7SK (63% identical). Paralogues in human: 7SK (73% identical), RN7SKP255 (73% identical), RN7SKP203 (73% identical), RN7SKP189 (72% identical), RN7SKP211 (71% identical), RN7SKP187 (71% identical), RN7SKP180 (71% identical), RN7SKP217 (71% identical), RN7SKP25 (71% identical), RN7SKP3 (71% identical), RN7SKP62 (71% identical), RN7SKP79 (71% identical), and 284 more.